SOD1 (superoxide dismutase 1)
Diseases named in the same sentence as SOD1 in open-access papers (continued):
Sharing a sentence is not in itself a finding about the gene and the disease.
glioma (continued). "Results analysis showed significant down-regulation of SIRT4 (p = 0.0337), SIRT5 (p<0.0001), GDH (p = 0.0305), OGG1-2α (p = 0.0001), SOD1 (p<0.0001) and SOD2 (p<0.0001) in glioma patients compared to controls." (PMID 36809279, 2023). "Before the testing of SOD1 inhibitor on cell survival in glioma, the expression of SOD1, SOD2 and SOD3 in U251 and U87 glioma cell lines was measured." (PMID 35978820, 2022). "The expression of SOD1 was upregulated in glioma grade III and V tissues compared with that in normal brain tissues or glioma grade I tissues." (PMID 35978820, 2022). "However, the expression of SOD1 in gliomas is still unknown." (PMID 35978820, 2022). "In glioma cells, KLF9 was identified to suppress the expression of SOD1, accomplishing the regulatory effects of GPR17 on ROS level." (PMID 34120140, 2021). "Thus, SOD isoforms, especially SOD2 and SOD1, have two functions in glioma and glioblastoma: they shield tumor cells from oxidative stress and help them become resistant to treatment." (PMID 40867576, 2025). "Together, these findings imply that SOD1 may be a target for glioma treatment and that the breakdown of PARP and BRCA1 may also be involved in the cell death brought on by SOD1 suppression." (PMID 40867576, 2025). "By targeting SOD1, ATN-224 may disrupt the ROS-regulatory network within glioma cells, which could have profound implications for tumor behavior and therapeutic response." (PMID 39187509, 2024). "Present study was purposed to figure out the expression level of mitochondrial sirtuins (SIRT3, SIRT4, SIRT5) and related genes (GDH, OGG1-2α, SOD1, SOD2, HIF1α and PARP1) in 153 glioma tissue samples and 200 brain tissue samples from epilepsy patients (taken as controls)." (PMID 36809279, 2023). "In this study, SOD1 inhibitor LCS-1 induced ROS production, activated ROS signal pathway in glioma cells, indicating that LCS-1 may induce cell death in gliomas." (PMID 35978820, 2022). "In glioma grade II tissues, non-sample was SOD1 negative staining, two samples were SOD1 weak staining, four samples were SOD1 moderate staining and 6 samples were SOD1 strong staining." (PMID 35978820, 2022). "In glioma grade IV tissues, non-sample was SOD1 negative staining, non-sample was SOD1 weak staining, 8 samples were SOD1 moderate staining and 10 samples were SOD1 strong staining." (PMID 35978820, 2022). "In glioma adjacent tissues, non-sample was SOD1 negative staining, one sample was SOD1 weak staining, five samples were SOD1 moderate staining, and four samples were SOD1 strong staining." (PMID 35978820, 2022). "In this study, SOD1 inhibitor LCS-1 induced time- and dose-dependent cell death in glioma cells." (PMID 35978820, 2022). "SOD1 expression was also reduced in glioma cell lines when compared to non-malignant cell controls." (PMID 36142793, 2022). "In glioma grade I tissues, non-sample was SOD1 negative staining, three samples were SOD1 weak staining, six samples were SOD1 moderate staining, and three samples were SOD1 strong staining." (PMID 35978820, 2022). "However, the effect of SOD1 inhibition on glioma therapy is not understood." (PMID 35978820, 2022). "In glioma grade III tissues, non-sample was SOD1 negative staining, one sample was SOD1 weak staining, five samples were SOD1 moderate staining and 16 samples were SOD1 strong staining." (PMID 35978820, 2022).
memory impairment (35 papers, 2012 to 2025). "Many SOD1 mutation carriers perform similarly to healthy controls on cognitive tasks, showing no significant memory impairment, language deficits, or executive dysfunction." (PMID 40649976, 2025).
coronary artery disease (34 papers, 2008 to 2025). "Other studies have reported that melatonin supplementation stimulated SOD1 in coronary artery disease or upregulated the SOD1 to deal with the neuronal damage caused by enhanced oxidative stress induced by PCBs in adult rats." (PMID 34683825, 2021). "Patients with coronary artery disease demonstrated elevated expression of SOD1 and SOD2 but not SOD3." (PMID 38389898, 2024).
epilepsy (34 papers, 2014 to 2024). A brain disorder characterized by episodes of abnormally increased neuronal discharge resulting in transient episodes of sensory or motor neurological dysfunction, or psychic dysfunction. "Decreased activity of CAT and SOD1 in the plasma suggests a reduced antioxidant defense capacity in epilepsy patients." (PMID 33082886, 2020).
cardiac hypertrophy (33 papers, 2013 to 2025). "A previous study using pressure overload induced cardiac hypertrophy model showed that fisetin markedly reduced ROS by increasing expression of SOD1, CAT and HO1." (PMID 37627641, 2023). "In this model we detected increased BP and heart hypertrophy together with increased CD concentration, SOD activity, and SOD1, eNOS, and NF-κB (p65) protein expressions." (PMID 27148433, 2016). "In conclusion, by comparing SOD1−/− with WT mice, we found that SOD1 function in the vasculature is limited under physiological conditions, but in the presence of Ang II, it causes aortic hypertrophy independent of the pressure increase response." (PMID 33809716, 2021). "For example, EA could significantly reduce markers of cardiac hypertrophy and apoptosis, as well as elevated expression of antioxidant enzymes including superoxide dismutase-1 (SOD1) in SHRs." (PMID 30719053, 2019).
endometriosis (33 papers, 2009 to 2025). The growth of functional endometrial tissue in anatomic sites outside the uterine body. "SOD1 is highly expressed in the cumulus cells of women with infertility and moderate and severe endometriosis and is positively associated with oocyte quality or clinical pregnancy rate following ICSI." (PMID 37296777, 2023). "The ratio of SOD1/GPx3 significantly decreased along with the growing prevalence of the endometriosis (P = 0.0048; 0.324 ± 0.110) and endometrial cancer (P = 0.0003; 0.123 ± 0.027) compared with the healthy controls (1.154 ± 0.336)." (PMID 37968795, 2024). "A significant decrease in relative gene expression of SOD1 (P < 0.0001) was determined in the endometriosis group (0.004 ± 0.001) and in the endometrial cancer group (0.008 ± 0.001) in comparison with the control group (0.033 ± 0.004)." (PMID 37968795, 2024). "In contrast to SOD1, SOD2 expression is upregulated in cancer cells and ovarian cancer cells associated with endometriosis." (PMID 37968795, 2024). "In addition, the lower SOD1 expression was found in oocytes of the experimental group with endometriosis." (PMID 37968795, 2024). "Interestingly, the analysis of SOD1 gene expression based on free circulating mRNA which showed a significant decrease in both the patients with endometrial cancer and endometriosis suggests that the SOD1 have a limited impact on the overall SOD activity in serum." (PMID 37968795, 2024). "Minimal changes in the overall activity of SOD measured in the serum (SOD1 and SOD3) of the patients with endometriosis and endometrial cancer could be therefore caused by a similar Cu/Zn ratio in these groups as both elements are required for the activation of Cu/Zn SODs." (PMID 37968795, 2024). "MenSC-EV treatment normalised oxidative-stress indices (SOD1, GPX4), restored PR-B expression, and decreased lesion area by more than 60% in mice with endometriosis." (PMID 41296460, 2025).
liposarcoma (33 papers, 2011 to 2025). A usually painless malignant tumor that arises from adipose tissue. "Autosomal dominant mutations have been primarily, but not exclusively, related to ALS, namely, the C9orf72, superoxide dismutase 1 (SOD1), transactive response DNA binding protein (TARDBP) and fused in sarcoma/translocated in liposarcoma (FUS/TLS) mutation, among others." (PMID 39728753, 2024). "Many gene mutations are responsible for causing familial ALS such as mutations in PFN1, FUS/TLS (fused in sarcoma/translocation in liposarcoma), TARDBP or TDP-43 (TAR-DNA-binding protein 43), UBQLN2, C9ORF72, SOD1 (superoxide dismutase 1), HNRNPA1, OPTN, and VCP." (PMID 27878120, 2016). "However, pathogenic variants in superoxide dismutase 1 (SOD1), hexanucleotide repeat expansions in chromosome 9 open reading frame 72 (C9ORF72), fused in sarcoma/translocated in liposarcoma (FUS), and transactive response DNA binding protein 43 (TDBP43) have been the most widely studied." (PMID 33810425, 2021). "At present, the four major ALS-associated genes are the chromosome 9 open reading frame 72 (C9ORF72), Cu-Zn superoxide dismutase 1 (SOD1), TAR DNA-binding protein 43 (TARDBP), and fusion in malignant liposarcoma/translocation in liposarcoma (FUS/TLS), in addition to at least other 40 genes." (PMID 32487123, 2020). "Mutations in several genes are causative for FALS, including fused in sarcoma/translated in liposarcoma (FUS), superoxide dismutase-1 (SOD1), TAR DNA-binding protein (TARDBP), angiogenin (ANG), vesicle-associated membrane protein B (VAPB), optineurin (OPTN), and valosin-containing protein (VCP)." (PMID 23577159, 2013).
prostate carcinoma (33 papers, 2014 to 2025). A carcinoma that arises from epithelial cells of the prostate gland. "SOD1 was identified as overexpressed in prostate cancer xenograft animals resistant to mitoxantrone (MTX), an antineoplastic agent used in CRPC." (PMID 36672191, 2023). "This study found that both PIN and prostate cancer had lower SOD1, SOD2, and catalase than benign tissue, results that support data reported earlier." (PMID 34943029, 2021). "SOD1 is a soluble Cu/Zn enzyme that is mainly located in the cytosol, although a small percentage of SOD1 proteins (~ 3%) is found in the intermembrane space of the mitochondria; SOD1 was found to decrease pso-mediated ROS in prostate cancer, inducing tumor cell growth and metastasis." (PMID 31847905, 2019). "Treatment with 50 nM 1,25(OH)2D3 increased the production of SOD1 and SOD2 in prostate epithelial cells (PEC) and androgen-sensitive prostate cancer cells (LNCaP)." (PMID 41009006, 2025). "ROS related gene SOD1 was increased after H2O2 treatment in all the cell lines, suggesting that prostate cancer cells were indeed experienced a high level of oxidative stress no matter a subtype of PCa cells." (PMID 30658679, 2019). "Calcitriol induced the expression of superoxide dismutase 1 (SOD1) and 2 (SOD2) in prostate epithelial cells (PECs) and in androgen-sensitive prostate cancer cells (LNCaP), respectively." (PMID 29657326, 2018). "Interestingly, we found high expression of antioxidant genes; SOD1, TXN, LAMTOR5, and ATOX1 in prostate cancer patients having higher ERG fusion expression." (PMID 35508713, 2022). "The superoxide dismutase (SOD) family consists of SOD1, SOD2, and SOD3 proteins that neutralize the first oxygen-derived ROS and provide protection against the development of cancers, including prostate cancer." (PMID 34943029, 2021). "The expression of antioxidant enzymes SOD1, SOD2, and catalase are lower in prostate cancer than in normal tissue." (PMID 39000269, 2024).
ulcerative colitis (33 papers, 2008 to 2025). An inflammatory bowel disease involving the mucosal surface of the large intestine and rectum. "Furthermore, the G allele of the SOD1 rs2070424 polymorphism decreases the risk of ulcerative colitis; thus, it might be assumed that the G allele has a protective role also in this disease." (PMID 35566673, 2022). "The aim of the present study was to analysis the relationship between the genetic polymorphisms of SOD1, CAT and GSHPX1 and the prevalence of IBD, including Crohn’s disease and ulcerative colitis among the Polish population." (PMID 29312611, 2017). "The main aim of this study was investigate the association between the genetic polymorphism of antioxidant enzyme genes: SOD1, CAT and GSHPX1 and the risk of inflammatory bowel disease (IBD), including Crohn’s disease and ulcerative colitis in the Polish population." (PMID 29312611, 2017).
chronic kidney disease (32 papers, 2013 to 2025). Impairment of the renal function secondary to chronic kidney damage persisting for three or more months. "Nrf2 regulates the expression of antioxidant enzymes and related proteins, such as SOD1, thereby helping cells alleviate oxidative damage, inflammation, and chronic kidney disease." (PMID 40611883, 2025). "It is possible therefore that felids may have lower levels of SOD1 and SOD3 in their kidney per se, which could predispose them to oxidative damage which, over time, progresses toward chronic renal disease." (PMID 32081923, 2020). "Furthermore, our own group showed for superoxide dismutase 1 in monocytes from chronic kidney disease patients an increased mRNA level together with reduced superoxide dismutase 1 protein content." (PMID 27630759, 2016).
proteinopathy (32 papers, 2008 to 2026). "It is noteworthy that, in carriers of SOD1 or FUS mutations, TDP-43 pathology is rarely observed, but their cognate SOD1 or FUS encoded proteinopathy abounds." (PMID 40252666, 2025). "The prime examples of ALS proteinopathy are inclusions formed by mutated superoxide dismutase 1 (SOD1) and ubiquitylated/phosphorylated TAR DNA-binding protein 43 (TDP43) that cannot be cleared by proteasomal and autophagic degradation machinery." (PMID 33343494, 2020). "Our findings demonstrate that SOD1 mutations in human MNs cause cell-autonomous proteinopathy, axonopathy, synaptic pathology, and aberrant neurotransmission." (PMID 33328898, 2020). "Two case reports have described cytoplasmic pTDP-43 proteinopathy in patients with SOD1 mutations." (PMID 36385230, 2023). "Subcortical white matter pathways in HIE cases showed salient vulnerability to proteinopathy; Olig2-positive oligodendrocytes were positive for oxidized/misfolded SOD1." (PMID 40277911, 2025). "Although our work has made relevant contributions to the potential of trehalose to protect against Sod1 proteopathy, a central mechanism of ALS disease, future tests on more complex ALS models are necessary." (PMID 39061876, 2024). "This quartet leads to proteinopathies like SOD1 and TDP-43 in the case of ALS, β-amyloid protein in the case of AD, and α-synuclein in the case of PD." (PMID 37759540, 2023). "As a broadly consistent ALS disease phenotype is associated with either TDP-43, SOD1, or FUS proteinopathies, it is likely they reflect earlier events which promotes aggregation amongst other neurotoxic effects." (PMID 35002606, 2021). "The human genome-edited SOD1-G93A MNs, as well as MNs generated from a patient-derived iPSC line with SOD1-A4V, developed robust disease phenotypes including proteinopathy, structural attrition, axonopathy, synaptic pathology, and functional defects." (PMID 33328898, 2020). "We next examined the SOD1-G93A mice at two different age groups (pre-symptomatic sentinel and symptomatic end-stage cohorts) to detect alterations in proteinopathy and gliosis burden." (PMID 33257786, 2020). "First, we used ubiquitin immunostaining to evaluate the proteinopathy alterations in the SOD1-G93A mice." (PMID 33257786, 2020). "Unique proteinopathies are also a feature of SOD1- and FUS-related familial ALS." (PMID 40563773, 2025). "It is tempting to speculate that PC-OxPL accumulation triggers or enhances TDP-43 and SOD1 proteinopathy in ALS by initiating molecular events related to kinase activity, and that those can be mitigated in the presence of PC-OxPL-VecTab®." (PMID 40697273, 2025). "Besides being able to prevent proteopathy, trehalose disaggregates Sod1 after the induction of proteopathy." (PMID 39061876, 2024). "These radicals can act as a determinant to trigger the biochemical conformational trajectories via changing the cellular redox thiol (SH) status of several proteins leading to misfolding and toxic proteinopathies in NDDs like amyloid β in AD, α-synuclein in PD and SOD1, and TDP-43 in case of ALS." (PMID 37759540, 2023). "Moreover, the cytoplasmic mislocalization, aggregation, and co-aggregation of TDP-43, FUS, and SOD1 can be identified as proteinopathies akin to other neurodegenerative diseases (NDs), eliciting strong ties to disrupted RNA splicing, transport, and stability." (PMID 32422969, 2020). "We hypothesize that toxic SOD1 conformers are formed as part of this replication process analogous to the proposed formation of toxic species in other protein misfolding disorders such as prion disease and tauopathies." (PMID 20498711, 2010). "Together, these findings suggest that SOD1 damage, induced by glycation or ALS-linked mutation, may affect TDP-43 phosphorylation status and promote its cytosolic mislocalization and aggregation, providing new insights into ALS-associated proteinopathy." (PMID 42074053, 2026).
proteinopathy (continued). "The accumulation of particular misfolded and aggregated proteins (ALS related proteins: TDP-43, SOD1, FUS) play a crucial role in the pathogenesis of the so called “protein misfolding disorder” ALS." (PMID 34439885, 2021). "SOD1G93A mice, as well as ALS patients harboring SOD1 mutations, do not develop the TDP-43 proteinopathy seen in 95% of ALS patients." (PMID 41268542, 2025). "We demonstrate close spatial relationships between disordered SOD1, pathological TDP-43 and p62 pathologies within these neurons, suggesting interactions between these proteins modulate the formation of their respective proteinopathies." (PMID 36008843, 2022). "Another potential mechanism underlying CSF-induced neurodegeneration, given the increasing recognition of ALS as a proteinopathy and the growing evidence supporting the prion-like properties of several key ALS proteins, notably that of TDP-43 and SOD1, is proteostasis." (PMID 33094283, 2020). "This could also be the case with certain disorders that are in the clinical and neuropathological spectrum of TDP-43 proteinopathies but which are TDP-43-negative, such as SOD1-positive MND and certain FTLD-U cases." (PMID 18657254, 2008). "The main protein aggregates related to proteinopathies are: amyloid β (Aβ) peptide and Tau protein in AD; α-synuclein (α-syn) in PD, transactive response DNA-binding protein of 43 kDa (TDP-43) in AD and ALS; Cu, Zn-superoxide dismutase (SOD1) in ALS; and Huntingtin protein (Htt) in HD." (PMID 34959337, 2021). "Given our observation of aggregated SOD1:YFP reporter in the JNPL3 model of spinal tauopathy, we next sought to determine whether the effects we observed were specific to tau or could be extended to a different type of spinal proteinopathy." (PMID 29776378, 2018). "Another potentially relevant aspect of ALS pathology is TDP-43 proteinopathy, where TDP-43 tends to be excluded from the nucleus and present in cytoplasmic aggregates, which is present in the majority of ALS cases, but not in SOD1 and FUS53." (PMID 37020097, 2023). "Importantly, the coalescence of SOD1, TDP-43 and p62 proteinopathies has not been assessed in vitro or in vivo to date, and may inform on novel therapeutic approaches capable of slowing or halting the development of multiple damaging co-pathologies." (PMID 36008843, 2022).